TMEM223 (transmembrane protein 223)
Description:
Mitochondrial ribosome-associated protein involved in the first steps of cytochrome c oxidase complex (complex IV) biogenesis. Stimulates the translation of MT-CO1 mRNA and is a constituent of early MT-CO1 assembly intermediates.
Synonyms: MGC3196; Mrx15
Tractability: Antibody: UniProt predicts a signal peptide or a membrane-spanning region. PROTAC: ubiquitination databases record sites on it; its protein half-life has been measured.
Gene: Protein-coding gene on chromosome 11 (62,771,629 to 62,792,013, reverse strand). Ensembl gene ENSG00000168569.
Subcellular location: Mitochondrion inner membrane
Subcellular location (Human Protein Atlas): Mitochondria; Nuclear membrane; Nucleoplasm
Pathways (Reactome):
Metabolism: Complex IV assembly
Gene Ontology:
Molecular function: mitochondrial ribosome binding
Biological process: mitochondrial respiratory chain complex IV assembly
Cellular component: mitochondrial inner membrane; mitochondrion
Genetic constraint (gnomAD): Loss-of-function variants: 14 observed, 11.75 expected, observed/expected ratio (o/e) 1.19, 90% interval 0.78 to 1.78. The synonymous counts are far from expectation, so gnomAD's model fits this gene poorly and the ratio says little. Missense variants: 346 observed, 234.39 expected, observed/expected ratio (o/e) 1.48, 90% interval 1.35 to 1.61. Synonymous variants: 145 observed, 105.56 expected, observed/expected ratio (o/e) 1.37, 90% interval 1.2 to 1.58.
Homologues: Orthologues: chimpanzee TMEM223 (99% identical), macaque TMEM223 (94% identical), rabbit TMEM223 (79% identical), dog TMEM223 (78% identical), pig TMEM223 (77% identical), guinea pig TMEM223 (76% identical), mouse Tmem223 (74% identical), rat Tmem223 (73% identical), tropical clawed frog tmem223 (44% identical), zebrafish tmem223 (44% identical), Drosophila melanogaster CG12935 (32% identical).